IL25 (interleukin 25)
Diseases named in the same sentence as IL25 in open-access papers (continued):
Sharing a sentence is not in itself a finding about the gene and the disease.
Granuloma (1 paper, 2018). A compact, organized collection of mature mononuclear phagocytes, which may be but is not necessarily accompanied by accessory features such as necrosis. "Decreased pulmonary collagen deposition and granuloma size were also observed in mice deficient in IL-25 or its receptor followingS." (PMID 30345011, 2018).
Hyperglycemia (1 paper, 2014). An increased concentration of glucose in the blood. "Some studies reported that therapeutic administration of anti-CD3, anti-IL-17, anti-IL-25 antibodies and proinsulin DNA improved hyperglycemia in diabetic NOD mice." (PMID 25522369, 2014).
interstitial lung disease (1 paper, 2017). A diverse group of lung diseases that affect the lung parenchyma. "We therefore did not perform any subsequent assessments of IL-25 in other interstitial lung diseases." (PMID 28202030, 2017).
intestinal cancer (1 paper, 2025). "Recent studies linking IL-25 and IL-17RB to intestinal cancer warrant further characterization of this cytokine axis." (PMID 40074948, 2025).
intestinal inflammation (1 paper, 2017). "By promoting the secretion of thymic stromal lymphopoietin, epidermal growth factor, IL-10, IL-25, and transforming growth factor-β1 by intestinal epithelial cells, Gal1 can inhibit experimental intestinal inflammation." (PMID 28086216, 2017).
leukemia (1 paper, 2023). A malignant (clonal) hematologic disorder, involving hematopoietic stem cells and characterized by the presence of primitive or atypical myeloid or lymphoid cells in the bone marrow and the blood. "Furthermore, expression of the Tuft cell marker DCLK-1 (double cortin-like kinase-1) and IL-25, which is secreted by Tuft cells and regulates type 2 immune responses, increased in a time-dependent manner that coincided with the temporal kinetics of leukemia progression." (PMID 38042840, 2023).
lung adenocarcinoma (1 paper, 2019). A carcinoma that arises from the lung and is characterized by the presence of malignant glandular epithelial cells. "By targeting IL‐25 or its receptor may provide a potential therapy strategy for reversing cisplatin resistance of human lung adenocarcinoma." (PMID 31044552, 2019). "In this study, we found that both IL‐25 and MVP were elevated expressed in cisplatin‐resistant lung adenocarcinoma cell line (A549/CDDP)." (PMID 31044552, 2019).
lymphedema (1 paper, 2021). Excess fluid collection in tissues, causing swelling. "Interestingly, we found that patients with lymphedema have significantly increased expression of Th2-inducing cytokines (TSLP, IL33, IL25) in the epidermal cells of the lymphedematous limb, and that treatment with QBX258 decreased or normalized these changes." (PMID 34571811, 2021).
lymphoma (1 paper, 2022). A malignant (clonal) proliferation of B- lymphocytes or T- lymphocytes which involves the lymph nodes, bone marrow and/or extranodal sites. "Some of these genes (such as the BTG2 gene, MYD88 gene and IL-25 genes) have been found to be closely related to the progression, chemotherapy resistance and inferior OS of lymphoma, and some have become potential therapeutic targets." (PMID 36221115, 2022).
mastocytosis (1 paper, 2015). A clonal myeloproliferative neoplasm characterized by the proliferation and accumulation of neoplastic mast cells in one or multiple organs or organ systems. "Our finding that IL-25 is essential for vaccine-driven effector responses is somewhat surprising because it has been largely considered to be (alongside IL-33 and TSLP) a key inducer cytokine, acting at an early stage to drive ILC2s, mastocytosis and, in turn, Th2 immunity." (PMID 25816012, 2015).
mental disorder (1 paper, 2024). A disease that has its basis in the disruption of mental process. "Emerging alarmins in cognitive and mental disorders including HMBG1, S100, IL-33 and its soluble receptor, soluble ST2, while among type 2 alarmins, less is known about the roles of TSLP and IL-25, but IL-25 could be important in maintaining blood-brain barrier (BBB) integrity." (PMID 39071802, 2024).
metabolic syndrome (1 paper, 2019). A cluster of metabolic risk factors for CARDIOVASCULAR DISEASES and TYPE 2 DIABETES MELLITUS. "The increased concentration of IL-33 and IL-25 in the VAT observed in our study in association with the low-grade inflammation linked to metabolic syndrome constitute a primary signal vital for ILC2 activation." (PMID 30755607, 2019).
metastatic colorectal cancer (1 paper, 2022). "Moreover, IL25 expression was associated with poor survival in patients with metastatic colorectal cancer." (PMID 35359953, 2022).
myelodysplastic syndrome (1 paper, 2021). A clonal hematopoietic disorder characterized by dysplasia and ineffective hematopoiesis in one or more of the hematopoietic cell lines. "Other studies have shown clinical efficacy of treatments with allogeneic NK cells activated with IL-25 or stimulated with IL-15, IL-12, and IL-186 in AML or myelodysplastic syndrome (MDS) patients." (PMID 33665226, 2021).
nasopharyngeal carcinoma (1 paper, 2022). A carcinoma arising from the nasopharyngeal epithelium. "Further, miR-515-5p can negatively control interleukin 25 (IL25) levels and sensitize resistant cells to cisplatin as well as to 5-FU in nasopharyngeal cancer." (PMID 35055115, 2022).
nephritis (1 paper, 2024). Inflammation of renal tissue. "We hypothesize that GL may promote the differentiation of M2 macrophages and alleviate Con A-induced nephritis by regulating the expression of IL-25 in the kidneys." (PMID 38785317, 2024). "The results showed that, consistent with the trend of the action of IL-25, GL could also promote the production of M2 in Con A-induced nephritis." (PMID 38785317, 2024). "Therefore, in this study, we aimed to explore whether GL affects the progression of Con A-induced nephritis by regulating the IL-25/M2 axis." (PMID 38785317, 2024). "We wanted to investigate whether GL can alleviate Con A-induced nephritis by regulating IL-25." (PMID 38785317, 2024).
neuromyelitis optica spectrum disorder (1 paper, 2020). "However, IL-17E/IL-25 has been shown to be elevated in plasma in a neuroinflammatory disorder, neuromyelitis optica spectrum disorder." (PMID 32804078, 2020).
nonalcoholic fatty liver disease (1 paper, 2019). "Our previous studies also showed that IL-25 reduced body weight gain and lipid accumulation by stimulating Type-2 macrophages (M2) polarization in nonalcoholic fatty liver disease (NAFLD)." (PMID 31296243, 2019).
osteoarthritis (1 paper, 2020). A noninflammatory degenerative joint disease occurring chiefly in older persons, characterized by degeneration of the articular cartilage, hypertrophy of bone at the margins and changes in the synovial membrane. "Serum from patients with RA and osteoarthritis (OA), and healthy controls, and synovial fluid from patients with RA and OA were collected, and the levels of IL-22 and IL-25 were measured." (PMID 32972460, 2020).
pancreas disease (1 paper, 2020). "Further, IL-25 itself has been shown to suppress tumorigenesis in a number of cancer models, including PDA, consistent with a protective role for tuft cells in pancreas disease." (PMID 32116793, 2020).
pancreatic ductal adenocarcinoma (1 paper, 2020). An infiltrating adenocarcinoma that arises from the epithelial cells of the pancreas. "Secrete IL-25 to promote epithelial recovery and inhibit the initiation of pancreatic ductal adenocarcinoma." (PMID 32733896, 2020).
pancreatitis (1 paper, 2020). Inflammation of the pancreas. "Given the established role for this cytokine as a tuft cell effector, we used several orthogonal methods to determine if IL-25 is expressed in pancreatitis tuft cells." (PMID 32116793, 2020). "While, IL-25 is an attractive candidate to study tuft cell function in pancreatitis, our RNA-seq analysis identified a number of other potential candidates, which also play a role in mediating inflammation and deserve further investigation." (PMID 32116793, 2020). "We also show that pancreatitis tuft cells express cytokine IL-25." (PMID 32116793, 2020).
parasite (1 paper, 2012). "Indeed, in type-2-skewed responses, such as some parasite infections in the gut, IL-25 clearly drives the inflammation upstream of IL-4, IL-5, and IL-13 and therefore acts as a pro-inflammatory cytokine." (PMID 22539101, 2012).
peritonitis (1 paper, 2018). Inflammation of the peritoneum (tissue that lines the abdominal wall and covers most of the organs in the abdomen). "In the current study, we show that IL-25, IL-33, and TSLP expression increased in response to systemic inflammation caused by experimental peritonitis, and sepsis induces expansion of ILC2 in the lungs consistent with the changes in the expression of IL-25, IL-33, and TSLP." (PMID 29511181, 2018).
pollen allergy (1 paper, 2019). "In relation to pollen allergy and GM-SCF, this cytokine has been reported to increase with IL-33 and IL-25 in animal models, and following the activation of neutrophils and antigen-specific T cells." (PMID 31817806, 2019).
psoriasis vulgaris (1 paper, 2018). Plaque psoriasis is the most common presentation of psoriasis. "Thus, IL-25 may play a certain inhibitory role in the pathogenesis of psoriasis vulgaris." (PMID 30345318, 2018).
rhinitis (1 paper, 2022). An inflammation of the mucous membrane lining the nose, usually associated with nasal discharge. "In particular, alarmin cytokines such as IL-25, IL-33, and TSLP are strongly associated with the development of rhinitis due to PM exposure." (PMID 35378908, 2022).
Skin rash (1 paper, 2023). A red eruption of the skin. "At 6 months of age, IL-25-producing cells increased in a time-dependent manner, even when the acute phase of the skin rash had abated." (PMID 36834723, 2023).
Sm (1 paper, 2019). "Furthermore, a recent study showed that IL-33 needs to synergize with two other cytokine alarmins, thymic stromal lymphopoietin (TSLP) and IL-25, to induce IL-4/IL-13-dependent inflammation and fibrosis after Sm infection." (PMID 31200771, 2019).
viral respiratory tract infection (1 paper, 2016). A respiratory tract infection caused by a virus. "TSLP has not previously been recognized to affect ILC2s during viral respiratory tract infection; however, it is a known stimulus of ILC2s in other disease models and can be released from epithelial cells in a fashion to IL-33 and IL-25." (PMID 27156176, 2016).
infection (100 papers, 2009 to 2026). The state of being infected such as from the introduction of a foreign agent such as serum, vaccine, antigenic substance or organism. "One study has observed susceptibility to HD Tm infection in IL‐25 knockout mice: a subsequent study has replicated this finding, and observed a reversal of susceptibility when IL‐25‐elicited progenitor immune cells were transfused into knockout mice." (PMID 40944312, 2025). "Recent studies demonstrated that intestinal tuft cells expand rapidly in response to enteric pathogens infection, which is associated with infection-induced interleukine-25 (IL-25) expression." (PMID 39261649, 2024). "During later stages of infection, these cells respond to IL-25 and IL-33 to promote the activation of pathogenic T helper cells that favor fungal survival and support cryptococcal dissemination to the brain." (PMID 37337050, 2023). "What is of great interest is that pathogenic infection is also reported to be one of the factors that induce IL-25 secretion." (PMID 36119076, 2022). "IL-25-deficient mice infected with pathogenic microorganisms cannot to eradicate the infection, which coincides with a failure in Th2-type immunity." (PMID 35999776, 2022). "Our group showed that mice susceptibility to primary infection with the intestinal trematode Echinostoma caproni depends on the inability of mice to respond to IL-25 production." (PMID 36176223, 2022). "During infection, levels of IL-25 significantly decrease, which is associated with an enhancement of type 2 responses, while increasing levels of IL-23, which promotes TH17 responses via IL-17." (PMID 34360770, 2021). "Results of worm recovery show that after the levels of IL-25 mRNA expression had declined, mice were once again susceptible to infection." (PMID 33276813, 2020). "Previous studies of our group showed that IL-25 is crucial for resistance to E. caproni and the susceptibility of mice relies on the inability of this host species to produce IL-25 in response to infection." (PMID 32616023, 2020). "Mice were susceptible to the challenge infection despite the development of a Th2 phenotype with elevated levels of IL-4 and IL-13 gene expression but low levels of endogenous expression of IL-25." (PMID 33276813, 2020). "Alternative activation of macrophages induced by IL-25 can be implicated in the resistance to infection." (PMID 33276813, 2020). "Subsequently, neutralization of IL-25 during the course of infection or use of IL-17RB deficient mice reduced airway mucus measured by PAS staining, and accumulation of IL-5 and IL-13 measured in re-stimulated draining lymph node cell supernatants." (PMID 32397226, 2020). "The inability of mice to produce IL-25 in response to primary infection and, consequently, IL-13 results in susceptibility to infection." (PMID 33276813, 2020). "IL-25−/− mice were then shown to be unable to expel T. muris, while genetically susceptible mice given exogenous IL-25 became resistant to infection." (PMID 31024526, 2019). "The mice strain AKR/OlaHsd, susceptible to infections and used in this study, registered comparable IL-25 expression levels both in the MLN and the caecum." (PMID 28404797, 2017). "In terms of T. muris infection, mice deficient in IL-25 (IL-25 KO mice) are susceptible to infection, showing reduced Th2 cytokine production and impaired mucin responses, with the phenotype being reversed by MPPtype2 cell transfer." (PMID 23053395, 2012). "Treatment of mice with a cocktail of antibiotics abrogated the IL-25 response after the curation of the primary E. caproni infection concomitantly with a decrease in bacterial abundance in feces and susceptibility to challenge infection at 2 wppi." (PMID 36176223, 2022). "Most of pathogenic infection induces the up-regulation of IL-25." (PMID 36119076, 2022).
infection (continued). "However, it was shown that infection with the intestinal worm Nippostongylus brasiliensis triggers epithelial cells to release IL-25 and IL-33, which in turn cause ILC2 expansion in mice." (PMID 32140157, 2020). "Related studies have demonstrated that IL-25 functions to promote protective immune response against T. spiralis infection by augmenting Th2 and Th9 cytokine production; however, the cellular mechanisms underlying IL-25-mediated immune response during infection remain elusive." (PMID 28898280, 2017). "Our results support IL-25 induces resistance to E. caproni infection and that susceptibility to primary infection relies on the the inability of mice to express IL-25 in response to infection." (PMID 27658962, 2016). "Immunity to challenge infection was compromised in IL-4Rα- and IL-25-deficient mice, despite levels of specific antibody comparable to immune wild-type controls, while deficiencies in basophils, eosinophils or mast cells or CCR2-dependent inflammatory monocytes did not diminish immunity." (PMID 25816012, 2015). "Evidence is robust that IL‐25 contributes to expulsion of Nb via ILC2s, with a role to play in Hp immunity, complicated by the chronic course of infection." (PMID 40944312, 2025). "Upon exposure to external insults such as injury and infection, the epithelium releases alarmins including interleukin-25 (IL-25), IL-33, and thymic stromal lymphopoietin (TSLP), which assist in initiating and amplifying the immune response." (PMID 41246133, 2025). "We found an increase in the gene expression of epithelial-derived IL-25 and IL-33 on day 3 after infection in adult cells." (PMID 40143308, 2025). "Similar to i.n. papain and IL-33+IL-25 activation of ILC2s, Blimp-1 was expressed in lung ILC2s five days after infection." (PMID 40297693, 2025). "Exposure to either IL-25 or Enterovirus 71 early in murine life induced greater tuft cell proliferation upon re-infection, and IL-25 training specifically reduced Enterovirus burden." (PMID 41155384, 2025). "Mice undergoing RV1B infection on day 6 of life and sham infection on day 13 showed significantly increased mRNA and protein expression of IL-25 on day 20 of life compared with sham-infected mice." (PMID 38061015, 2024). "Keratinocytes respond to skin damage and/or infection by producing “alarmin” cytokines: IL-25 (IL-17E), IL-33, and thymic stromal lymphopoietin (TSLP)." (PMID 36830738, 2023). "The expression of adiponectin in the intestinal tissue of IL-25 receptor knockout (Il17rb−/−) mice that lack endogenous IL-25 signaling was examined and compared with that of wild-type mice after infection with T. spiralis for 7 days." (PMID 37635188, 2023). "Infection with NTHi is also associated with transcriptional upregulation of cytokines CCL2 (MCP1), TNF, IL-1β, IL-6, CXCL8 and alarmins (TSLP, IL-33 and IL-25)." (PMID 37180449, 2023). "In the experiments against N. brasiliensis, it has been shown that, after 5 days of infection, the IL-25 activated iILC2s to highly express IL-13, IL-5 and IL-4, and only the iILC2s expressed the Th2 cytokines." (PMID 37173731, 2023). "Using multicolor flow cytometric analysis, we first characterized the kinetics of IL-17RB, the cognate receptor for IL-25 expression on lung CD4+ T helper cells during pulmonary C. neoformans H99 infection for 3, 7, and 14 days." (PMID 37337050, 2023). "We observed that C. neoformans infection promoted a predominant increase of T helper cells that co-expressed IL-25 and IL-33 receptors within the lung during the late infection phase." (PMID 37337050, 2023). "Upon infection with helminths, intestinal epithelial cells produce alarmins (e.g., IL-25) and activate ILC2s to secrete IL-13, which induces differentiation of intestinal stem cells into tuft and goblet cells, important for parasite expulsion." (PMID 36430676, 2022).